NLRP3 (NLR family pyrin domain containing 3)
Diseases named in the same sentence as NLRP3 in open-access papers (continued):
Sharing a sentence is not in itself a finding about the gene and the disease.
infection (continued). "Since the extracellular toxins accumulate with time, they may cause massive NLRP3-independent cell death in the late stage of infection." (PMID 34009097, 2021). "However, treatment of mice from day 1 postinfection with the highly efficacious small‐molecule NLRP3 inhibitor MCC950 rendered mice more susceptible to infection, raising safety concerns regarding potent ablation of NLRP3 responses as a therapeutic strategy." (PMID 33834544, 2021). "We speculate that it may be beneficial to partially inhibit NLRP3 inflammasome to prevent infection susceptibility, which could be a side effect of inflammasome inhibition." (PMID 34321581, 2021). "Interestingly, NLRP3 deficiency resulted in higher levels of IL-1β in the brain later in infection, suggesting a regulatory role for NLRP3 in modifying caspase-1 activity rather than simply increasing IL-1β activation in response to an immune stimulus." (PMID 33524073, 2021). "Significantly lower levels of Mannose-1 receptor required for the entry of Francisella into the cells in Nlrp3−/− mice indicate that Nlrp3 allows the silent bacterial entry into the cells that may also enhance the host’s susceptibility to infection." (PMID 34690967, 2021). "However, our observations here indicate that infection with IAV which lacks NS1 led to the loss of NLRP3 inflammasome activation and IL-1β release, while enhancing the assembly of SGs and induction of IFN-β." (PMID 33766561, 2021). "Similarly, infection of these cells with RSV yielded a drastic loss of IL-1β production since NLRP3 and ASC are required for RSV-mediated inflammasome activation." (PMID 32854254, 2020). "Although this review focuses only on direct inhibition of the NLRP3 inflammasome, there is significant interest in the inhibition of upstream processes, which again may lessen the risk of infection." (PMID 33255820, 2020). "Thus, the NLRP3 inflammasome is considered as a stress sensor that detects loss of homeostasis and abnormal endogenous molecules that signal infection, metabolic abnormalities or tissue damage." (PMID 32849554, 2020). "To further explore whether the enhanced survival and viral clearance in Parkin-deficient mice are dependent on NLRP3-activated antiviral inflammation, we next performed infection studies in Parkin and NLRP3 double knockout mice." (PMID 31229895, 2019). "Moreover, infection with influenza A virus in mice deficient in Nod2 and Ripk2 results in defective mitophagy, leading to excessive activation of NLRP3 and increased IL-18 production." (PMID 31590215, 2019). "During infection, viroporins, which are a group of virus-encoded proteins that enhance the permeability of host cell membrane, and some viral functional proteins play an important role in stimulating the NLRP3 inflammasome through Signal II." (PMID 30858838, 2019). "In vivo infections performed in inflammasome-deficient mice indicate that NLRP3 is involved with footpad swelling, inflammation and pain, establishing a role of the NLRP3 inflammasome in the MAYV pathogenesis." (PMID 31479495, 2019). "However, in L. major infections, NLRP3 inflammasome activation appeared to be associated with infection susceptibility." (PMID 31233552, 2019). "Although the role of NLRP3 inflammasome in immune response is well defined, the mechanism underlying its assembly modulated by pathogen infection remains largely unknown." (PMID 28060938, 2017). "Biofilms of encapsulated C. neoformans, opsonized and encapsulated C. neoformans, and acapsular yeast forms of C. neoformans stimulate formation of the NLRP3 inflammasome, and mice deficient in components of the NLRP3 inflammasome are more susceptible to infection." (PMID 28936464, 2017). "In another study using a murine model of systemic PCM induced by intravenous infection, the susceptibility of NLRP3 and caspase-1 knockout mice to P. brasiliensis infection was evaluated and their increased susceptibility was associated with reduced IL-18 production and Th1 immunity." (PMID 28740491, 2017).
infection (continued). "Interestingly, a recent work describes the recruitment of two sensor proteins (NLRC4 and NLRP3) to the same inflammasome complex as a result of the recognition of different danger signals from the same pathogenic infection." (PMID 28191008, 2017). "Because the human disease is thought to be acquired by the pulmonary route, and diverse routes of infection induce different patterns of immunity and disease severity, in the present study, we sought to investigate the role of NLRP3 inflammasome in the pulmonary infection caused by P. brasiliensis." (PMID 28740491, 2017). "Recent studies have found that soluble UA and UA crystals activate the NLRP3 (NLR family pyrin domain containing 3) inflammasome, causing proinflammatory cytokines such as IL-1β to mature and trigger congenital immune defence against danger signals such as infection and metabolic disorder." (PMID 29358971, 2017). "Thus, during pathogenic infections, NLRP3 inflammasomes represent highly proinflammatory platforms that play critical roles in clearing microbial infection and alerting the immune system." (PMID 29375379, 2017). "However, following lethal infection with Francisella, IL-1r-, Caspase-1/11-, Asc- and Aim2-deficient mice exhibited increased susceptibility as expected, while Nlrp3-deficient mice were more resistant." (PMID 27926940, 2016). "Compared to uninfected cells, while the infection of TOE-A5 caused reduction in ubiquitinated NLRP3, the amount of the ubiquitinated NLRP3 in the TOE-A5/nleA-infected cells did not decrease but increased, indicating that NleA directly or indirectly influence this step of inflammasome activation." (PMID 26332984, 2015). "In silico data using the GP63-cleavage motif indicated a possible GP63-mediated processing of inflammasome or inflammasome-associated proteins, including NLRP3 and pro-IL-1β, which we were able to confirm in infection experiments of both murine BMDMs and human THP-1 macrophages." (PMID 26114647, 2015). "Notably, IL-1β and IL-18 secretion are abrogated during infection of NLRP3-deficient (Nlrp3−/−) BMDMs with ΔflaA Lp in both primed and unprimed macrophages." (PMID 23762026, 2013). "However, when infected with double mutant of VopQS (ΔtdhASΔvopQS), the IL-1β release in infected NLRP3-deficient macrophages was enhanced to a similar extent as that upon infection with ΔtdhΔh1." (PMID 23357873, 2013). "However, LDH release from NLRC4-deficient cells was considerably decreased by infection with ΔtdhASΔh1, raising the possibility that some effectors encoded in the h1 region affect NLRP3-mediated LDH release in a caspase-1 activation-independent manner." (PMID 23357873, 2013). "Finally, in the late phase of infection, the level of IL-1β was significantly lower in NLRP3-deficient mouse in comparison with wild type mice and was not detectable in IL-1β-deficient mouse (data not shown)." (PMID 19696895, 2009). "Moreover, IL-1β production can result from activation of inflammasomes other than NLRP3 or via inflammasome-independent pathways, raising concerns that IL-1β-specific blockade may impair host defense and increase infection risk." (PMID 41231359, 2025). "Since NLRP3 is involved in many important cellular processes, including immune defense and tissue repair, blocking its activity could lead to unintended consequences including impairing pathogen clearance and thus increasing the risk of infection." (PMID 38892264, 2024). "Thus, miR-7 may reduce the antiviral response against virus infections and predispose the host to develop a severe infection by blocking NLRP3." (PMID 37508374, 2023). "It is tempting to speculate that the STEC type III secretion system (T3SS) is implicated since our results indicated that NLRP3 is involved in IL-1β secretion, and previous studies showed that Salmonella enterica induces NLRP3 activation upon THP-1 infection associated with the activity of the T3SS." (PMID 38127952, 2023).
infection (continued). "Although targeting the NLRP3 inflammasome has to date been shown to be effective in slowing disease progression and onset, there are currently no approved treatments which can ablate and/or downregulate its activity, a consequence of side effects and increased susceptibility to infection." (PMID 35755447, 2022). "Moreover, the activation of NLRP3 inflammasome is tightly regulated by distinct EV-encoded proteins via different mechanisms, highlighting the importance of NLRP3 inflammasome during EVs infection." (PMID 36026486, 2022). "Besides the infection-related danger signal molecules, such as nigericin and double stranded RNAs, the endogenous damaged-associated molecules were also found to trigger the activation of NLRP3 inflammasome." (PMID 35879806, 2022). "However, further studies are needed to determine the role of Pak and NLRP3 during infection in humans and whether Pak/NLRP3 signaling axis deficiencies are associated with increased susceptibility to infection." (PMID 33914853, 2021). "It is important to note that, generally, biologics targeting the NLRP3/IL-1β pathway target secreted IL-1β directly, like Canakinumab to suppress its inflammatory responses, which poses a serious risk of fatal infection, as IL-1β cannot be produced in response to an infection." (PMID 34439904, 2021). "Therefore, NLRP3 inflammasome may have different effects in specific conditions, including physiological condition, infection by invading pathogenic bacteria and involving in innate immune disorder." (PMID 34707607, 2021). "However, dysregulation of the NLRP3 inflammasome and pyroptosis results in pathological inflammation during infection and is associated with pathogenesis in multiple disease conditions, including inflammatory autoimmune diseases, metabolic, degenerative, and neuroinflammatory diseases." (PMID 32630319, 2020). "Therefore, NLRP3 deficiency influences expression of IL-4 and Ym1 in the lung during infection with N. brasiliensis and may control release of Ym1 by alveolar Mφs in the airways." (PMID 31586037, 2019). "Therefore, it is reasonable to deduce that IL-1β and the NLRP3 inflammasome are important for the control of the infection caused by Leishmania, and also that the parasite has developed mechanisms to subvert the immune system, interfering with IL-1β synthesis/response." (PMID 31233552, 2019). "Understanding how pathogens activate the NLRP3 inflammasome may provide insight into the mechanisms of host defense against microbes and is essential for developing potential treatment approaches against pathogenic infections." (PMID 31417575, 2019). "However, the excessive ER stress generated by infection may cause intracellular Ca2+ and ROS disruption that inhibits NLRP3 inflammasome assembly through the ROS–iNOS–NO axis." (PMID 30214444, 2018). "However, epithelial Nlrc4 deficiency, more than Nlrp3, resulted in significantly enhanced Candida buccal load throughout the 21-day infection period and increased inflammatory cell recruitment in the tongue epithelium despite the presence of erosive lesions and hyphae." (PMID 27592079, 2016). "The exact nature of the NLRP3 activating signal remains somewhat elusive although production of reactive oxygen species (ROS), mitochondrial dysfunction, potassium efflux, calcium mobilization, have been implicated in NLRP3 inflammasome activation during infection." (PMID 24312100, 2013). "Consistently, targeted retinal and cortical proteomics reveal dysregulated bacterial-infection pathways, including a Chlamydia interactome coupled to NLRP3-inflammasome signaling." (PMID 41571675, 2026). "Infection activates the NLRP3 inflammasome via ROS, cathepsin B, and potassium efflux, promoting IL-1β/IL-18 secretion and ASC oligomerization." (PMID 42245999, 2026). "Mechanistically, IBV infection promotes K+ efflux and Ca2+ mobilization, which together facilitate NLRP3 inflammasome activation." (PMID 41979900, 2026).
infection (continued). "In this study, we focused on the role of the Nlrp3 inflammasome during ST infection, since this inflammasome has been found to regulate neutrophil and macrophage numbers in zebrafish larvae under homeostasis and sterile inflammation." (PMID 41360763, 2025). "NLRP3 inflammasome was also reported to mediate lung pathology in a mouse model of A. baumannii pneumonia, while others found that the NLRP3 inflammasome was protective against infection with a clinical isolate of this bacterium." (PMID 40202049, 2025). "In the nasal tissue, the expression of endosomal TLRs, cytosolic RLRs and NLRP3 increased with infection in both genotypes, but levels (with the exception of TLR7) were higher in TLR7 KO mice." (PMID 40442368, 2025). "Together, these data demonstrate that under infection conditions in which Mtb alone minimally induced inflammasome assembly, Mtb-specific mAbs complexed to Mtb potently stimulate NLRP3-dependent inflammasome activation and IL-1β secretion." (PMID 40747430, 2025). "Initially, some DCs activate caspase-11 and NLRP3 inflammasome-dependent pyroptosis early during infection." (PMID 40530878, 2025). "The data showed that the infection of murine macrophages with M. smegmatis increased NLRP3 expression by 32.9% compared to the control group." (PMID 40142455, 2025). "This can promote a pro-inflammatory M1 phenotype and initiate activation of the NLRP3 inflammasome—a key innate immune sensor that detects cellular stress and infection." (PMID 40870916, 2025). "Coxsackievirus A16 (CV-A16) and A10 (CV-A10) infections promote pyroptosis mediated by NLRP3 and increase the release of inflammatory cytokines." (PMID 40593504, 2025). "PRRSV-2 infection enhanced the interaction between NLRP3 and ASC, promoting NLRP3 inflammasome assembly in PAMs, similar to the effect of LPS plus nigericin." (PMID 39869629, 2025). "In this study, we discovered that NLRP3 deficiency in macrophages affects the expression of key glycolytic enzymes, such as Pkm and HK1, following infection." (PMID 41190868, 2025). "Collectively, these results indicate that C. albicans infection initiates macrophage inflammatory responses through the TLR4/NF-κB/NLRP3 pathway, amplifying tissue inflammation via cascading effects and leading to severe infection." (PMID 41008953, 2025). "The mRNA expression levels of NLRP3 and Caspase 1 in the infection group were raised compared to the control group (p < 0.001)." (PMID 40427615, 2025). "In K18-hACE2 mice, NLRP3 inflammasome activation and IL-1β release are observed late in infection (7 dpi), coinciding with fatal disease progression." (PMID 40016339, 2025). "Actin clusters were observed in HFF cells infected with HSV‐1 by 4 h post‐infection, where caspase‐1 colocalizes and terminates NLRP3 inflammasome formation." (PMID 39878363, 2025). "SARS-CoV-2 dampens NLRP3 inflammasome activation, inducing the immune escape mechanism at the early stage of infection, while it requires activation to propagate later." (PMID 40568785, 2025). "Retroviruses like HIV-1 exemplify Parkin-dependent mechanisms, where infection of central nervous system microglia activates the NLRP3 inflammasome." (PMID 40317036, 2025). "The results showed that a dose-dependent elevation in NLRP3 expression as the infection dose increased." (PMID 40092991, 2025). "CMPK2 (KME = 0.943) is a mitochondria-localized ISG that couples TLR/IFN signals to mtDNA synthesis and NLRP3 inflammasome activation in macrophages, aligning with inflammatory injury mechanisms in infection." (PMID 41465783, 2025). "To confirm that the reduction in neutrophil numbers during ST infection results from inflammasome-dependent cell death, we performed TUNEL staining in Nlrp3-deficient larvae." (PMID 41360763, 2025). "The NLRP3 inflammasome serves as the body’s primary protective response against infection or injury and plays a critical role in shaping the gut microbiome." (PMID 40433382, 2025).
infection (continued). "Excessive activation of NLRP3 inflammasome triggers intense inflammation, leading to severe tissue damage under various infections and stress signals." (PMID 39869629, 2025). "At the same time, in infection experiments using cagA+ and cagA− H. pylori strains in 2021, the expression levels of NLRP3, ASC, IL-1β, and IL-18 were higher as a result of cagA+ H. pylori infection compared to cagA− strains." (PMID 40563885, 2025). "ALKBH5 decreases the stability of NLRP3 mRNA by removing its m6A modification, thereby inhibiting macrophage NLRP3 inflammasome activation and weakening host resistance to infection." (PMID 40859309, 2025). "The NLRP3 inflammasome is a key cytosolic sensor in the innate immune system, activated by diverse danger signals such as metabolic stress, infections, and structural cellular disruptions." (PMID 40959087, 2025). "Myoinositol oxygenase expedited the activation of the NLRP3 inflammasome, contributing to cardiac dysfunction in infection-induced cardiac dysfunction models." (PMID 40307577, 2025). "The reduction in neutrophil NLRP3 inflammasome activation is a major element in the inherent vulnerability to infections in neonates and preterm infants, leading to an increase in morbidity and mortality." (PMID 41149694, 2025). "A significant increase in NLRP3 mRNA expression was observed with progressing infection, peaking at 16 hpi (11-fold increase compared to mock-infected cells)." (PMID 40510795, 2025). "Compared to the infection group, levamisole and 25 to 100 mg/kg of baicalin attenuated NLRP3 and Caspase 1 mRNA expression levels (p < 0.001)." (PMID 40427615, 2025). "Quantitative analysis revealed that NLRP3 exhibited the most significant modulation, with a 4.2-fold induction by infection and 68% suppression with ouabain (p < 0.01)." (PMID 40895521, 2025). "The NLRP3 and caspase-1 mRNA levels were increased in the infection group compared with the control group (p < 0.001)." (PMID 40305201, 2025). "During early infection, neutrophil‐derived extracellular traps (NETs) and elastase trigger mtROS bursts that activate the NLRP3 inflammasome in macrophages, reinforcing M1 polarization." (PMID 40584964, 2025). "GBP5 (guanylate binding protein 5) plays an important role in the assembly of the NLRP3 inflammasome in response to infection and a variety of inflammatory disease processes." (PMID 39924511, 2025). "Activation of the NLRP3 inflammasome constitutes a key axis in the innate immune response to damage or infection signals." (PMID 40959087, 2025). "This is consistent with prior bulk RNA-seq analysis of foot tissue from CHIKV-infected mice at day 30 post infection that also detected an ongoing inflammatory response including elevated Ifng, Il1b, Tnf, Nlrp3, numerous chemokines, and immunoproteasome genes." (PMID 40678223, 2025). "Many components of the classical inflammasome that are activated by Salmonella42, including Nlrp3, Casp1 and Gsdmd, are among those transcriptionally upregulated after 120 min of infection with either strain of Salmonella." (PMID 41188240, 2025). "In fact, the host can benefit from the defensive effects of the NLRP3 inflammasome in response to infection by a variety of bacteria, viruses, fungi, and parasites." (PMID 41357231, 2025). "The NLRP3 inflammasome induces the secretion of pro-inflammatory cytokines and controls the majority of immune mechanisms necessary to resist infections, such as acidification of the phagosome in mice." (PMID 41149694, 2025). "We detected the expression of major inflammasome genes (NLRP3, caspase-1, IL-1β, IL-18) during infection progression." (PMID 40906404, 2025). "Compared to the infection group, treatment with levamisole and 25 mg/kg–50 mg/kg of baicalin reduced the NLRP3 and Caspase 1 expression levels (p < 0.05)." (PMID 40427615, 2025).